MALAT1 (metastasis associated lung adenocarcinoma transcript 1)
Diseases named in the same sentence as MALAT1 in open-access papers (continued):
Sharing a sentence is not in itself a finding about the gene and the disease.
colon carcinoma (continued). "Inhibition of MALAT1 expression in colon cancer may promote apoptosis and hinder cell proliferation by suppressing the activation of Wnt/β-catenin signaling pathway." (PMID 31733641, 2020). "Interestingly, one study reported that MALAT1 inhibits colon cancer cell migration and invasion via regulation of EpCAM and ITGB4." (PMID 33246471, 2020). "In this study, we found that the knockout of MALAT1 lncRNA inhibited the proliferation and promoted the apoptosis of colon cancer cells and that both effects may be related to the inhibition of the Wnt/β-catenin pathway by MALAT1 knockout." (PMID 31733641, 2020). "MALAT1 expression was significantly higher in colon cancer vs. para-carcinoma tissues." (PMID 31733641, 2020). "MALAT1 is up-regulated in human colon cancer cell lines and inhibition of MALAT1 could reduce the proliferation of colon cancer cells." (PMID 31304004, 2019). "High expression of lncRNA MALAT1 suggests poor prognosis in colon cancer." (PMID 30984308, 2019). "Finally, in colon cancer cells, MALAT1-depletion is reported to decrease the nuclear localization of β-catenin thereby inhibiting wnt/β-catenin signaling." (PMID 27250026, 2016). "In colon cancer, MALAT-1 has increased expression in cancer tissue vs.normal." (PMID 27508057, 2016). "However, the role and mechanism of MALAT1 in colon cancer are still poorly understood." (PMID 31733641, 2020). "Our and others’ works indicate that miR663a inhibits the development and metastasis of colon cancer and that the miR663a target genes MALAT1 and TTC22 promote colon cancer metastasis." (PMID 37400477, 2023). "Downregulation of MALAT1 attenuates SW480 and HCT116 cell proliferation by acting a ceRNA to inhibit high motility group box protein 1 (HMGB1) via sponging miR-129-5p in colon cancer cells." (PMID 33246471, 2020). "Based on this assumption, we provide the first evidence that plant mtr-miR5754 and gma-miR4995 can significantly reduce the level of MALAT1 and NEAT1 in colon cancer cell lines." (PMID 33193626, 2020). "Namely, the level of lncRNA MALAT1 was increased in 5FU-resistant colon cancer subline HCT-116/5-FU compared to the parental HCT-116 cell line, while silencing of MALAT1 by siRNA was shown to increase the chemosensitivity of HCT-116/5-FU cells to treatment with 5FU." (PMID 35922756, 2022). "Furthermore, upregulation of MALAT1 enhances HIF-1 and endothelial cell protein levels, which influence colon cancer progression." (PMID 35571488, 2022). "lncRNA MALAT1 was upregulated in colon cancer tissues and may mediate HMGB1 by sponging miR-129-5p in colon cancer." (PMID 30984308, 2019). "The specimens that exhibited invasion (20 tumor tissues) had an equal frequency of MALAT1 unmethylation as compared to the group without family history of colon cancer, and this difference was not statistically significant (P = 0.197)." (PMID 32099603, 2019). "The role and mechanism of MALAT1 in colon cancer are not clear." (PMID 31733641, 2020).
glioblastoma (50 papers, 2013 to 2025). The most malignant astrocytic tumor (WHO grade IV). "The metastasis-associated lung adenocarcinoma transcript 1 (MALAT1) is a long non-coding RNA (lncRNA) implicated in cancer progression and metastasis in various cancers, including glioblastoma." (PMID 39457052, 2024). "The lncRNA metastasis-associated lung adenocarcinoma transcript 1 (MALAT1) has garnered significant attention as a therapeutic target in various cancers, including glioblastoma." (PMID 39015773, 2024). "Metastasis-associated lung adenocarcinoma transcript 1 (MALAT1) is an overexpressed lncRNA in glioblastoma and promotes cell growth and tumorigenesis." (PMID 36819921, 2023). "Metastasis-associated lung adenocarcinoma transcript 1 (MALAT-1) lncRNA was found to be targeted by miR-9 for decay inside the cell’s nucleus in glioblastoma cells." (PMID 37444408, 2023). "The LncRNA MALAT1-elevated expression is associated with the poor prognosis of glioblastoma patients." (PMID 36232466, 2022). "For example, KIAA0495/PDAM can act as tumor suppressors in oligodendrioglioma while MALAT1 (metastasis associated lung adenocarcinoma transcript 1) is related to different tumors being able to act as tumor suppressor in glioblastoma." (PMID 31709240, 2019). "For example, MALAT-1 induces EMT in various cancers via the Wnt/β-catenin signalling pathway, while loss of WIF1 enhances the migratory potential of glioblastoma cells through WNT5A activation mediated by MALAT1." (PMID 29701689, 2018). "Consistent with this speculation, elevated serum levels of MALAT1 have been associated with the poor response of patients with glioblastoma to TMZ." (PMID 34178658, 2021). "Also, this association was shown in Lnc-OC1/miR-34a/34c of OC and MALAT1/miR-101 of Glioblastoma (GBM) cells, respectively." (PMID 33632341, 2021). "This study showed the efficiency of the liposomal nanocomplex in cancer stem cell targeting and downregulation of MALAT1 by anti-MALAT1-siRNA, leading to decreased growth, stemness, and the migration of glioblastoma cells." (PMID 39457052, 2024). "Knockdown of MALAT-1 markedly enhanced the sensitivity of multi-resistant glioblastoma cells to Temozolomide (TMZ) by decreasing the expression level of the resistance genes MDR1, MRP5, and LRP1 as well as the mesenchymal markers ZEB1, α-SMA, and fibronectin." (PMID 38201661, 2024). "In glioblastoma, MALAT1 regulates numerous facets of tumor biology, particularly about GSCs, which are pivotal in tumor initiation and progression." (PMID 39015773, 2024). "Implicated in mediating therapeutic resistance in GSCs, MALAT1 confers resistance to chemotherapy, such as TMZ, and radiotherapy—standard treatments for glioblastoma." (PMID 39015773, 2024). "For instance, it was found that MALAT1 promoted TMZ resistance in glioblastoma multiforme (GBM) cells." (PMID 36829256, 2023). "In glioblastoma, si-MALAT1 downregulated the expression of ZEB1, MDR1, MRP5 and LRP1, enhancing the sensitivity to Temozolomide (TMZ)." (PMID 36829256, 2023). "In vitro and in vivo studies have shown that LncRNA MALAT1 facilitates glioblastoma cell proliferation and progression by reducing miR-199a to promote ZHX1 expression." (PMID 36232466, 2022). "The direct interaction of MALAT1 and miRNA was indicated by the significant upregulation of miR-203a-3p in si-MALAT1 transfected human glioblastoma cells resistant to temozolomide." (PMID 35922756, 2022). "The following lncRNAs engaged in glioblastoma therapy resistance were selected: MALAT1, CASC2, H19, TUSC7, XIST, RP11-838N2.4, DLX6-AS1, GLIDR, MIR210HG, SOX2-OT." (PMID 33245508, 2022). "In glioblastoma, lncRNA MALAT1 contributes to tumor proliferation and progression by MALAT1/miR-199a/ZHX1 axis." (PMID 33665208, 2021). "Meanwhile, down-regulation of WIF1 has been shown to enhance the migratory aptitude of glioblastoma via WNT5A that induces expression of MALAT1." (PMID 34178658, 2021).
glioblastoma (continued). "Administration of anti-MALAT1 siRNA via nanoparticles has enhanced response to TMZ in xenograft models of glioblastoma." (PMID 34178658, 2021). "The serum levels of MALAT1 have also been associated with poor response to TMZ and lower survival rate of patients with glioblastoma." (PMID 34576322, 2021). "Cancer stem cells showed upregulation of MALAT1 compared to differentiated cancer cells in glioblastoma." (PMID 34322395, 2021). "Functionally, MALAT1 confers this phenotype by inhibiting the miR-101 signaling pathway in glioblastoma cells." (PMID 34178658, 2021). "Determining treatment response: MALAT1 plays a major role in tumor chemosensitivity with a higher expression in temozolomide (TMZ)-resistant glioblastoma cells." (PMID 34322395, 2021). "A clinical study in this field has shown the association between elevated serum levels of MALAT1 and poor response to TMZ and low survival rate of patients with glioblastoma." (PMID 34178658, 2021). "Cell cycle and proliferation: MALAT1 knockdown resulted in tumor growth inhibition and induced cell cycle arrest at G1/S phase in glioblastoma (U251) cells putatively via regulating the miR-124/zinc finger E−box binding homeobox 2 (ZEB2) axis." (PMID 34322395, 2021). "A genome-wide expression profiling in glioblastoma cells has identified MALAT1 as one of the most remarkably over-expressed genes following treatment with temozolomide (TMZ)." (PMID 33634032, 2020). "MALAT1 silencing has increased sensitivity of patient-originated glioblastoma cells to TMZ and improved the effects of this drug in xenograft mice models." (PMID 33634032, 2020). "Targeting lncRNA MALAT1 (metastasis-associated lung adenocarcinoma transcript-1)/miR-199a/ZHX1 (zinc fingers and homeoboxes) exhibited anti-tumor activities in glioblastoma." (PMID 32322669, 2020). "MALAT1 promotes esophageal squamous cell proliferation and metastasis and can also increase glioblastoma cell migration." (PMID 32099603, 2019). "LncRNA MALAT1 is up-regulated in multidrug-resistant glioblastoma cell lines and decreases the sensitivity of glioblastoma cells to TMZ by up-regulating EMT-related proteins (ZEB1, Snail and SLUG)." (PMID 29458374, 2018). "Further, MALAT-1, a nuclear lncRNA, was reported to be targeted by miR-9 in an Ago-2-dependent manner in the nuclei of Hodgkin’s lymphoma and glioblastoma cell lines." (PMID 28715488, 2017). "MALAT1 is associated with EMT, which confers invasive capacity to malignant cells, and the depletion of MALAT1 can reduce the migration of glioblastoma cells." (PMID 27686732, 2016). "Interestingly, lncRNA MALAT1 was shown to downregulate miR-203a-3p levels in glioblastoma multiforme cells, thereby promoting TYMS expression." (PMID 35922756, 2022). "Likewise, the reduction of MALAT1 by delivering targeted nanoparticles carrying MALAT1 siRNA improved the sensitivity of glioblastoma to temozolomide." (PMID 34959397, 2021). "In particular, MALAT1 has been noted to be involved in the pathogenesis of glioblastoma." (PMID 34576322, 2021). "Notably, functional studies have verified that MALAT1 silencing reverses TMZ resistance in glioblastoma cell lines." (PMID 34178658, 2021). "have reported up-regulation of MALAT1 in TMZ-resistant glioblastoma cells." (PMID 34178658, 2021). "Moreover, MALAT1 promotes chemoresistance to TMZ in glioblastoma cells by repressing miR-101 and miR-203." (PMID 33980320, 2021). "The diagnostic power of lncRNAs SAMMSON, HOTAIR, MALAT1, H19, and LINR-ROR has been assessed in serum or tissue samples of pateints with glioblastoma revealing the best results for the first two mentioned lncRNAs based on the high values of the area under the reciver operating characteristic curves." (PMID 33634032, 2020).
glioblastoma (continued). "Recent studies have shown that MALAT1 acts as a competitor of cellular endogenous RNAs (ceRNAs), a class of short ncRNA, which serves as a ‘molecular sponge’ for miRNAs, leading to modulation of their downstream roles in glioblastoma." (PMID 32283739, 2020). "Moreover, MALAT1 has been described as highly expressed in glioblastoma, with its expression pattern corresponding to poor prognosis for glioblastoma patients." (PMID 32283739, 2020). "They showed MALAT1 upregulation in glioblastoma in vitro and in vivo." (PMID 32650527, 2020). "In addition, growing evidence indicates that lncRNAs have various roles in resistance to glioblastoma therapies (e.g., MALAT1, H19) and in glioblastoma progression (e.g., CRNDE, HOTAIRM1, ASLNC22381, ASLNC20819)." (PMID 32650527, 2020). "Importantly, targeted nanocomplexes carrying MALAT1-targeting siRNAs were able to eradicate glioblastoma stem cells, leading to improved sensitivity of tumor cells to temozolomide in animal models of glioblastoma." (PMID 29739426, 2018). "This suggests that MALAT1 could serve as a preclinical model for glioblastoma." (PMID 39015773, 2024). "In this work, we investigated the effect of conditions that reduce the proportion of CSCs in the GBM cell population on the levels of long noncoding RNAs (lincROR and MALAT1) involved in the formation of the phenotype of glioblastoma cancer stem cells." (PMID 36653583, 2023). "HOTAIR could promote glioblastoma cell cycle progression; FOXM1-AS could enhance self-renewal and tumorigenesis of glioblastoma stem-like cells; H19 could promote glioblastoma cell invasion, angiogenesis, and tube formation; MALAT1 could decrease the sensitivity of glioblastoma cells to TMZ." (PMID 34759954, 2021). "Moreover, silencing of MALAT-1 increased the sensitivity of glioblastoma cells to temozolomide." (PMID 33806782, 2021). "Therefore, molecular therapies based on MALAT1 knockdown could be a promising treatment for glioblastoma." (PMID 32283739, 2020). "Further research is necessary to unravel the specific mechanisms by which MALAT1 regulates GSC behavior and to develop effective MALAT1-targeting strategies for treating glioblastoma." (PMID 39015773, 2024). "Another preclinical study demonstrated that targeting MALAT1 with modified ASOs promotes the differentiation of tumor cells and decreases tumor growth in a breast cancer mouse model —a strategy that may be suitable for other solid cancers, including glioblastoma." (PMID 39015773, 2024). "Upon hypoxia, hypoxia-inducible factors (HIFs) modulate many ncRNAs, including MALAT1, the lncRNA HOTAIR in non-small cell lung cancer (NSCLC), and the lncRNA H19 in glioblastoma." (PMID 36012617, 2022). "MALAT-1, also known as nuclear-enriched abundant transcript 2 (NEAT-2), is one of the oncogenic lncRNAs with high expression level in glioblastoma tissues." (PMID 33806782, 2021). "In another study, it was reported that MALAT-1 knockdown resulted in the upregulation of miR-101 and downregulation of glycogen synthase kinase (GSK)-3β in resistant glioblastoma cells, hence overcoming the temozolomide-MDR in the cells." (PMID 33806782, 2021). "In glioblastoma patients under treatment with TMZ, MALAT1 expression was upregulated, showing resistance to drug treatment, through suppression of miR-203 and activation of thymidylate synthase (TS) mRNA function." (PMID 32283739, 2020). "The complex formed by MALAT1/miR-199a/ZHX1 promotes glioblastoma cell proliferation in vitro and in vivo, and correlates with glioblastoma progression in patients." (PMID 32283739, 2020). "Conversely, MALAT1 upregulation induced by N-Myc-activated JMJD1A gene expression enhances migration and invasion of glioblastoma cells." (PMID 27686732, 2016).
glioblastoma (continued). "In addition, MALAT1 is involved in EMT induction and thus regulates glioblastoma cell sensitivity to TMZ." (PMID 36819921, 2023). "MALAT-1 and H19 are well-studied lncRNAs in developing temozolomide MDR in glioblastoma." (PMID 33806782, 2021). "Wnt inhibitory factor 1 (WIF1) attenuates non-canonical Wnt signaling through downregulation of MALAT1, thereby suppressing migration, but not proliferation, of glioblastoma cells." (PMID 33980320, 2021). "have shown that MALAT1 silencing decreases migration of glioblastoma cells, without affecting proliferation." (PMID 34178658, 2021). "Notably, expressions of oncogenic lncRNAs lnc-TALC, LncSBF2-AS1, MALAT1, TP73-AS1, and H19 as well as expression of tumor suppressor lncRNAs AC003092.1, TUSC7, and RP11-838N2.4 have been shown to alter this phenotype in glioblastoma cells." (PMID 33634032, 2020). "MALAT1 is overexpressed in both glioblastoma tissue and serum of patients that do not respond to TMZ, in comparison to those that do." (PMID 32650527, 2020). "Furthermore, MALAT1 overexpression was reversed by WIF1-mediated attenuation of WNT signaling, which in turn inhibits glioblastoma cell migration." (PMID 27686732, 2016). "Up-regulation of a number of oncogenic lncRNAs such as H19, MALAT1, SNHGs, MIAT, UCA, HIF1A-AS2 and XIST in addition to down-regulation of other tumor suppressor lncRNAs namely GAS5, RNCR3 and NBAT1 indicate the role of these lncRNAs in the pathogenesis of glioblastoma." (PMID 33634032, 2020). "Meanwhile, MALAT1 caused tumor cell infiltration and drug resistance in glioblastoma multiforme (GBM), combining standard TMZ treatment with targeted nanocomplex carrying siRNA against MALAT1 substantially enhanced the very poor prognosis for GBM patients." (PMID 31391118, 2019).